NUB1 (negative regulator of ubiquitin like proteins 1)
Description:
Specific down-regulator of the NEDD8 conjugation system. Recruits NEDD8, UBD, and their conjugates to the proteasome for degradation. Isoform 1 promotes the degradation of NEDD8 more efficiently than isoform 2.
Synonyms: NYREN18; BS4; NUB1L
Tractability: Small molecule: a structure with a bound ligand is known. PROTAC: ubiquitination databases record sites on it; its protein half-life has been measured.
Gene: Protein-coding gene on chromosome 7 (151,341,708 to 151,378,461, forward strand). Ensembl gene ENSG00000013374.
Subcellular location: Nucleus
Subcellular location (Human Protein Atlas): Nucleoli; Nucleoplasm
Pathways (Reactome):
Metabolism of proteins: Neddylation
Gene Ontology:
Molecular function: protein binding
Biological process: positive regulation of proteasomal ubiquitin-dependent protein catabolic process; protein ubiquitination; response to tumor necrosis factor; response to type II interferon; ubiquitin-dependent protein catabolic process; regulation of ubiquitin-dependent protein catabolic process; proteasomal protein catabolic process
Cellular component: nucleolus; nucleoplasm; cytosol; Lewy body; nucleus
Genetic constraint (gnomAD): Loss-of-function variants: 21 observed, 41.52 expected, observed/expected ratio (o/e) 0.51, 90% interval 0.36 to 0.73. The upper end of that interval is the gene's LOEUF score, 0.73, which puts it in group 2 of 6, group 1 being the genes least tolerant of losing a copy. Missense variants: 447 observed, 489.51 expected, observed/expected ratio (o/e) 0.91, 90% interval 0.84 to 0.99. Synonymous variants: 179 observed, 190.33 expected, observed/expected ratio (o/e) 0.94, 90% interval 0.83 to 1.07.
Homologues: Orthologues: chimpanzee NUB1 (99% identical), macaque NUB1 (97% identical), dog NUB1 (93% identical), pig NUB1 (89% identical), rabbit NUB1 (88% identical), rat Nub1 (87% identical), mouse Nub1 (87% identical), guinea pig NUB1 (86% identical), tropical clawed frog nub1 (58% identical), zebrafish nub1 (40% identical), Drosophila melanogaster CG15445 (27% identical), Drosophila melanogaster CG5111 (27% identical).
Diseases named in the same sentence as NUB1 in open-access papers:
NUB1 is named in the same sentence as 24 diseases in open-access papers, as found by Europe PMC text mining. Sharing a sentence is not in itself a finding about the gene and the disease. The quoted sentences say what the papers report.
breast carcinoma (3 papers, 2021 to 2025). "For example, studies have revealed that NUB1 is a positive regulator of tumor proliferation in breast cancer." (PMID 40164590, 2025). "For example, NUB1 knockdown suppressed the growth of breast cancer cells in vitro by inducing cell cycle arrest." (PMID 40164590, 2025). "NUB1 is highly expressed in breast cancer, and its knockdown of NUB1 has been demonstrated to inhibit breast cancer cell proliferation." (PMID 40164590, 2025). "However, breast cancer patients with lower survival probability had low cytoplasmic NUB1 protein." (PMID 34571823, 2021).
gastric cancer (3 papers, 2021 to 2025). A primary or metastatic malignant neoplasm involving the stomach. "NUB1 exhibits conflicting roles across cancers: it suppresses gastric cancer via p27Kip1 upregulation, yet paradoxically induces cell cycle arrest in BC." (PMID 40564026, 2025). "Elevated NUB1 levels suppress tumour growth in gastric cancer by promoting p27Kip1 degradation, allowing the cell cycle to continue." (PMID 40564026, 2025). "Studies have demonstrated that NUB1 overexpression can inhibit the growth of a wide range of tumors, including renal cell carcinoma, osteosarcoma, and gastric cancer, by inhibiting NEDD8 and its conjugation system." (PMID 40164590, 2025). "In gastric cancer, NUB1 suppresses tumour growth by promoting p27Kip1 degradation, yet its role in BC, particularly in ERα signalling and FEC response, remains unexplored." (PMID 40564026, 2025). "A study found that decreased NUB1 levels were positively correlated to the poorer prognosis of gastric cancer (GC) patients." (PMID 34571823, 2021). "In addition, studies have revealed that NUB1 knockdown promotes tumor growth in renal cell carcinoma, osteosarcoma, and gastric cancer by upregulating NEDD8 and its conjugation system." (PMID 40164590, 2025).
renal cell carcinoma (3 papers, 2008 to 2025). "NUB1 has been examined in various cancer cell lines, including renal cell carcinoma (RCC), cervical adenocarcinoma, neuroblastoma, rectal adenocarcinoma, and malignant lymphoma." (PMID 34571823, 2021). "Clone Pr17 is identical to human NEDD8 ultimate buster-1 (NUB1) mRNA, which was detected in renal cell carcinoma (NY-REN-18, Genbank accession number AF155099)." (PMID 18949081, 2008).
Sepsis (3 papers, 2023 to 2025). Sepsis is defined as life-threatening organ dysfunction caused by a dysregulated host response to infection. "Other transcripts upregulated in CD5L− peritoneal cells, including Osm, Il18bp, Ripk1, Nub1, Tlr2, Stat1, Irf1, Nfkb1, Pik3r5, or their coding proteins, were already associated with sepsis severity." (PMID 38750020, 2024). "We identified COMMD9, CSF3R, and NUB1 as potentially biologically relevant genes and diagnostic markers for sepsis." (PMID 37449204, 2023). "We therefore investigated the relationship between COMMD9, CSF3R, and NUB1 expression and the infiltration of immune cells in specimens from patients with sepsis and healthy controls." (PMID 37449204, 2023). "We uncovered 50 DEGs between the cohorts that we further analyzed, resulting in prioritization of COMMD9, CSF3R, and NUB1 as potential biomarkers to diagnose sepsis." (PMID 37449204, 2023). "Recent similar studies have effectively utilized SVM-RFE to identify COMMD9, CSF3R, and NUB1 as potential biomarker genes for predicting sepsis, uncovering new mechanisms in disease pathogenesis that may offer opportunities for therapeutic intervention." (PMID 40535544, 2025). "In this study, we found that COMMD9, CSF3R, and NUB1 regulate immune cell infiltrate during sepsis, and we speculate that the activity of these genes may influence the development of sepsis." (PMID 37449204, 2023). "Only three genes were identified by both of the approaches: COMMD9, CSF3R, and NUB1, suggesting these genes may be involved in sepsis diagnose." (PMID 37449204, 2023). "This study is the first to propose and verify differential expression of COMMD9, CSF3R, and NUB1 in patients with sepsis, and ROC analysis confirmed that they may be useful as diagnostic biomarkers." (PMID 37449204, 2023). "Ultimately, we identified COMMD9, CSF3R, and NUB1 as genes that could potentially be used as biomarkers to predict sepsis, which we confirmed by ROC analysis." (PMID 37449204, 2023). "We identified three genes, COMMD9, CSF3R, and NUB1, that were differentially expressed in sepsis compared to non-pathological specimens, and we correlated the differential expression of these genes with the immune cell composition of immune infiltrate." (PMID 37449204, 2023).
Blindness (2 papers, 2012 to 2017). Blindness is the condition of lacking visual perception defined as a profound reduction in visual perception. "The proteasome regulator NUB1 was identified as an interacting partner of the inherited blindness protein AIPL1 in a yeast two-hybrid screen, suggesting AIPL1 may influence retinal protein degradation pathways through modulating NUB1 function." (PMID 22347407, 2012).
dementia with Lewy bodies (2 papers, 2019 to 2022). "In patients with PD and dementia with Lewy bodies (DLB), NUB1 has been found to co-localize with inclusions and accumulates in a the presynapses of the hippocampus, cerebral neocortex, and substantia nigra, at which some toxic species of the proteinase K-resistant α-synuclein are deposited." (PMID 30999567, 2019).
hepatocellular carcinoma (2 papers, 2025). A malignant tumor that arises from hepatocytes. "Another recent study complements that low NUB1 triggers tumour growth in hepatocellular carcinoma (HCC) via the PCNA-NEDD8 pathway, a well-established mechanism linked to elevated proliferation." (PMID 40564026, 2025). "However, the expression of NUB1 in hepatocellular carcinoma (HCC) and its effects on HCC growth remain unclear." (PMID 40164590, 2025).
Leber congenital amaurosis (2 papers, 2017 to 2023). Leber congenital amaurosis (LCA) is a retinal dystrophy defined by blindness and responses to electrophysiological stimulation (Ganzfeld electroretinogram (ERG)) below threshold, associated with severe visual impairment within the first year of life. "The list included genes associated with different forms of Leber congenital amaurosis, involved in disruptions in phototransduction (AIPL1), retinoid cycle (RDH12, RPE65), and transport across the photoreceptor connecting cilium (LCA5), as well as genes evidently interacting with AIPL1 (NUB1, AHR)." (PMID 38203368, 2023).
atherosclerosis (1 paper, 2015). A disease characterized by the build-up of fatty material and calcium deposition in the arterial wall resulting in partial or complete occlusion of the arterial lumen. "In the Chr 5 locus, there are 4 hepatic genes with eQTL that are in strong LD with the atherosclerosis associated SNP at the locus: Nub1 (p = 1.65×10−16), Nos3, (p = 3.08×10−6), Cdk5 (p = 2.48×10−5), and Abcb8 (p = 7.46×10−4)." (PMID 26694027, 2015).
dementia (1 paper, 2016). Loss of intellectual abilities interfering with an individual's social and occupational functions. "NUB1, a negative regulator of ubiquitin-like proteins, was shown to enhance proteasomal degradation of the aSyn-interacting protein synphilin-1, to enhance tau phosphorylation and aggregation, and to co-localize with presynaptic PK-resistant aSyn in the brains of patients with dementia with LB." (PMID 27322389, 2016).
Huntington disease (1 paper, 2022). Huntington disease (HD) is a rare neurodegenerative disorder of the central nervous system characterized by unwanted choreatic movements, behavioral and psychiatric disturbances and dementia. "Alternatively, inducing NUB1 by treatment with interferon-β decreased mHTT and rescued neuronal toxicity indicating NUB1 as a possible therapeutic target in Huntington’s disease." (PMID 39483771, 2022).
multiple system atrophy (1 paper, 2022). Multiple system atrophy (MSA) is a neurodegenerative disorder characterized by autonomic failure (cardiovascular and/or urinary), parkinsonism, cerebellar impairment and corticospinal signs with a median survival of 6-9 years. "NUB1 negatively regulates the levels of NEDD8, and NUB1 likely contributes to the pathogenesis of PD and other synucleopathies, such as LB dementia and multiple system atrophy." (PMID 39483771, 2022).
Parkinson disease (1 paper, 2018). A progressive degenerative disorder of the central nervous system characterized by loss of dopamine producing neurons in the substantia nigra and the presence of Lewy bodies in the substantia nigra and locus coeruleus. "Other genes that associate with Parkinson’s disease that were also repressed were NUB1 which encodes a Lewy body protein, and DJ-1 (aka PARK7) whose product can bind LRRK2 and is associated with a recessive form of Parkinson’s disease." (PMID 30374342, 2018).
psoriasis (1 paper, 2023). An autoimmune condition characterized by red, well-delineated plaques with silvery scales that are usually on the extensor surfaces and scalp. "Our GNN also succeeds in separating 83 healthy skin samples from 95 lesional psoriasis samples, revealing that upregulation of 26S- and NUB1-mediated degradation of NEDD8, UBD, and their conjugates is central to the largest perturbed reaction network component in psoriasis." (PMID 37521042, 2023).
cancer (2 papers, 2021 to 2025). A tumor composed of atypical neoplastic, often pleomorphic cells that invade other tissues. "Together, FAT10 and NUB1 could serve as novel prognostic and diagnostic biomarkers to prognosis and predict survivability in cancer patients." (PMID 34571823, 2021). "It is possible that NUB1 is oncogenic and is associated with less aggressive cancer pathways." (PMID 34571823, 2021). "Overexpression of NUB1 in cancer cells is associated with IFN-α induced antimitogenic activities." (PMID 34571823, 2021). "FAT10 protein is a major player in cancer invasion, metastasis, and development, while NUB1 has a potential anticancer role." (PMID 34571823, 2021). "In contrast, upregulated NUB1 expression prevented cancer cell multiplication and hindered the G1/S cell cycle phase transition in GC cells." (PMID 34571823, 2021). "In contrast, the depleted NUB1 might provide a prognosis for poor survival in cancer patients." (PMID 34571823, 2021). "Since NUB1 controls the cell cycle progression via the upregulation of p27Kip1, overexpression of NUB1 and NUB1L may prevent the activities of SCF family proteins via suppressing the ligase activity of SCF complexes to treat malignant phenotypes in cancer cells." (PMID 34571823, 2021). "Several studies investigated the correlation between the NUB1 and FAT10 proteins and the survival probability among cancer patients." (PMID 34571823, 2021). "NUB1 and FAT10 mRNA expressions were overexpressed in numerous cancers relative to adjacent normal cells." (PMID 34571823, 2021). "NUB1 is an interferon-inducible protein that mediates apoptotic and anti-proliferative actions in cancer, while FAT10 is a ubiquitin-like modifier that promotes cancer." (PMID 34571823, 2021). "The upregulated expression of both NUB1 and FAT10 has been observed in various cancers." (PMID 34571823, 2021). "Specifically, NUB1/NUB1L non-covalently binds to NEDD8 through their UBA domains to prevent its aberrant effects in cells and, ultimately, the development of cancer." (PMID 34571823, 2021).
infection (2 papers, 2013 to 2015). The state of being infected such as from the introduction of a foreign agent such as serum, vaccine, antigenic substance or organism. "We confirmed that CecA1 and Dipt were also up-regulated in nub1 mutants after treatment with antibiotics, excluding that excessive expression in nub1 mutants is caused by ongoing infections." (PMID 24010524, 2013). "Among the interferon-stimulated proteins, two apoptosis-associated molecules (including NUB1 and STAT1) and two autophagy-associated proteins (including SQSTM1 and Irgm1) were significantly up-regulated only in the Hep-dG infection group." (PMID 26217322, 2015). "In response to infection, activation is dominant and repression is to a large extent alleviated, leading to strong immune gene expression in both wt and nub1 flies; at the same time, some de-repression was evident in nub1 mutants." (PMID 24010524, 2013). "To eliminate the possibility that the high level of AMP gene expression was due to the presence of an ongoing infection, and not the nub1 mutation, we treated flies with a potent cocktail of antibiotics prior to the analysis." (PMID 24010524, 2013). "In nub1 mutants, which lack Nub-PD protein, excessive expression of antimicrobial peptide genes occurs in the absence of infection, leading to a significant reduction of the numbers of cultivatable gut commensal bacteria." (PMID 24010524, 2013). "However, due to large biological variation in transcriptional response to infection, especially in the nub1 mutant, the difference was not statistically significant." (PMID 24010524, 2013).
tumours (2 papers, 2021 to 2025). "Cytoplasmic NUB1 levels were significantly higher in ER-negative tumours (mean IPS: 35.5) compared to ER-positive BCs (mean IPS: 23.6)." (PMID 40564026, 2025). "Unlike proliferation markers such as Ki-67, which broadly predict tumour aggressiveness, NUB1’s role in FEC-specific cell cycle arrest offers a chemotherapy-focused prognostic tool." (PMID 40564026, 2025). "Our study identifies NUB1 as a novel tumour suppressor and predictive biomarker in BC, with dual roles in FEC chemotherapy response and ERα regulation." (PMID 40564026, 2025). "The aggressive tumour was characterised by low cytoplasmic NUB1, showing high levels of apoptosis with high proliferation." (PMID 34571823, 2021). "For example, ER-negative patients with low cytoplasmic NUB1 (mean IPS = 1.1% vs. 60.0%) in high-cytoplasmic NUB1 tumours may benefit from alternative regimens, such as CDK4/6 inhibitors, to bypass defective cell cycle checkpoints." (PMID 40564026, 2025). "Our study builds on a patented IHC methodology (Malaysian Patent Application No. PI2024002978), titled “Method for Detecting the Expression of NUB1 in Human Tumour Tissue”, filed on 1 May 2024, and developed as part of this research study." (PMID 40564026, 2025). "NUB1-positive and -negative tumours could be very different in in biological features." (PMID 34571823, 2021).
bacterial infection (1 paper, 2013). "In response to bacterial infection, expression of CecA1, Dipt and Drs mRNAs was potently activated both in wt control and nub1 flies." (PMID 24010524, 2013).
NUB1 also shares sentences with these, for which no sentence is quoted: AIDS (1 paper); dysplasia (1); melanoma (1); osteosarcoma (1); ovarian carcinoma (1); viral infection (1).